UNC5B (unc-5 netrin receptor B)
Diseases named in the same sentence as UNC5B in open-access papers (continued):
Sharing a sentence is not in itself a finding about the gene and the disease.
ovarian carcinoma (3 papers, 2022 to 2024). A malignant neoplasm originating from the surface ovarian epithelium. "NTN4 was present in ovarian cancer cells, and its corresponding receptor, UNC5B, was identified in fibroblasts." (PMID 39135097, 2024). "UNC5B was highly expressed in ovarian cancer, and its expression was negatively correlated with the prognosis of ovarian cancer patients." (PMID 35035481, 2022). "The expression of UNC5B was decreased in ovarian cancer tissues after silencing UNC5B expression compared with the shRNA-NC group." (PMID 35035481, 2022). "OA inhibits proliferation, invasion, and clonogenesis of ovarian cancer cells by inhibiting UNC5B and increases the antitumor activity of niraparib." (PMID 35035481, 2022). "Although the function and mechanism of UNC5B in ovarian cancer have been preliminarily studied in this study, there are still some deficiencies." (PMID 35035481, 2022). "Retrieval results showed that UNC5B expression was significantly elevated in ovarian cancer (426 serous ovarian cancer) compared with normal ovarian tissue (n = 88)." (PMID 35035481, 2022). "In this study, the pathway and method of UNC5B affecting ovarian cancer cell migration were investigated." (PMID 35035481, 2022). "CCK-8 assay was used to detect cell proliferation, transwell assay was used to evaluate cell migration, and clonogenesis assay was used to evaluate the effect of UNC5B on ovarian cancer cell proliferation." (PMID 35035481, 2022). "The biological effect of UNC5B on ovarian cancer was further verified by tumor-bearing assay in nude mice." (PMID 35035481, 2022). "At the same time, the effect of UNC5B on ovarian cancer cell proliferation and invasion was verified." (PMID 35035481, 2022). "TCGA database was used to analyze the expression of UNC5B in ovarian cancer and its relationship with prognosis." (PMID 35035481, 2022). "This study shows that UNC5B is highly expressed in ovarian cancer tissues compared with normal ovarian tissues." (PMID 35035481, 2022). "Compared with the shRNA-NC group, the expression of E-cadherin in ovarian cancer tissues after silencing UNC5B expression was upregulated, while expression of vimentin was downregulated." (PMID 35035481, 2022). "UNC5B was highly expressed in ovarian cancer cells SKOV3 and OVCA420 compared with normal ovarian epithelial cells." (PMID 35035481, 2022). "In animal studies, knockdown of UNC5B inhibited tumor proliferation in a tumor-bearing model of ovarian cancer." (PMID 35035481, 2022). "OA can inhibit the expression of UNC5B and inhibit the proliferation and metastasis of ovarian cancer." (PMID 35035481, 2022). "In this study, qRT-PCR was used to detect the expression of UNC5B in ovarian cancer tissues and adjacent normal tissues." (PMID 35035481, 2022). "Immunohistochemistry results showed that the positive rate of UNC5B in ovarian cancer tissues was significantly higher than that in normal adjacent tissues, with a statistically significant difference." (PMID 35035481, 2022). "The results showed that UNC5B was overexpressed in ovarian cancer tissues." (PMID 35035481, 2022). "The expression of UNC5B in ovarian cancer cells was detected by qPCR assay." (PMID 35035481, 2022). "The expression of UNC5B in ovarian cancer and adjacent normal tissues was analyzed by qRT-PCR." (PMID 35035481, 2022). "The expression of UNC5B in ovarian cancer was analyzed by the TCGA database." (PMID 35035481, 2022). "UNC5B is expected to be a new potential therapeutic target for ovarian cancer." (PMID 35035481, 2022). "In addition, OA inhibited the proliferation and migration of ovarian cancer cell lines by inhibiting the expression of UNC5B." (PMID 35035481, 2022). "However, the role of UNC5B in ovarian cancer needs to be further studied." (PMID 35035481, 2022). "Therefore, UNC5B has a potential value as a marker and therapeutic target for ovarian cancer." (PMID 35035481, 2022).
ovarian carcinoma (continued). "OA inhibits ovarian cancer cell proliferation, migration, and EMT by targeting UNC5B and increases the antitumor effect of niraparib." (PMID 35035481, 2022). "Moreover, four neural genes (NTN1, UNC5B, EFNB2, and EFNA5) were nominated as promising biomarkers and therapeutic targets in ovarian cancer patients." (PMID 39456618, 2024). "In addition, silencing UNC5B inhibits the proliferation, invasion, clonogenesis, and EMT processes of ovarian cancer cells." (PMID 35035481, 2022). "Therefore, UNC5B may affect EMT through Snail1 expression, thereby promoting ovarian cancer migration." (PMID 35035481, 2022).
prostate carcinoma (3 papers, 2018 to 2025). A carcinoma that arises from epithelial cells of the prostate gland. "Similarly using flag‐labelled lentivirus, we transfected UNC5B to Renal carcinoma cells (786‐0, ACHN), prostate cancer cells (22RV‐1) and BC cells (UMUC3), and examined the apoptosis." (PMID 33345442, 2021).
Cerebral ischemia (2 papers, 2021 to 2024). Restriction of arterial blood supply to the brain associated with insufficient oxygenation to support the metabolic requirements of the tissue. "Alternatively, a study on cerebral ischemia demonstrated that after stroke, NTN4 is upregulated in astrocytes and blood vessels of the ischemic core, and DCC but not UNC5B is upregulated in neuronal processes." (PMID 33923095, 2021).
colorectal tumor (2 papers, 2021 to 2024). "Collectively, our results show that UNC5B-Δ8 and NOVA2 are upregulated in colorectal tumor vasculature." (PMID 34381052, 2021).
diabetic retinopathy (2 papers, 2014 to 2019). "Therefore, UNC5B could be a novel target for the therapy of diabetic retinopathy, retinopathy of prematurity, and other ocular neovascular diseases." (PMID 25149138, 2014). "Furthermore, it has been described that proteolytic fragments of Netrin-1, signalling trough UNC5b, can increase the vascular permeability in diabetic retinopathy, a phenomenon that we cannot rule out in our system." (PMID 30897795, 2019).
gestational diabetes (2 papers, 2019 to 2021). Carbohydrate intolerance first diagnosed during pregnancy. "Another published study described UNC5B to be downregulated using human umbilical vascular endothelial cells in an angiogenesis model for gestational diabetes in the placenta." (PMID 33923095, 2021).
lung carcinoma (2 papers, 2016 to 2021). "Some of these genes, e.g., EGR1 and UNC5B, are known to be associated with different cancers, including lung cancer." (PMID 33711952, 2021). "In conclusion, the study report here is the first to unravel Naa10 as the negative regulator of NTN1 and its receptor UNC5B in human lung carcinoma cell lines and caudal half region of E10 mouse embryos." (PMID 27910960, 2016). "The expression of UNC5A, UNC5B, or UNC5C is down-regulated in multiple cancers including lung cancer, and UNC5B has also been indicated as a putative tumor suppressor." (PMID 33711952, 2021).
pancreatic cancer (2 papers, 2017 to 2020). "In contrast, study in pancreatic cancer have reported that netrin-1 inhibited tumor growth by interfering with integrin β4 expression through UNC5B/FAK signaling." (PMID 28710382, 2017).
renal cell carcinoma (2 papers, 2022 to 2025). "Differential expression of UNC5B and UNC5C was found in renal cell carcinoma (KIRC, KIRP, and KICH)." (PMID 41407823, 2025).
acute kidney injury (1 paper, 2021). Sudden and sustained deterioration of the kidney function characterized by decreased glomerular filtration rate, increased serum creatinine or oliguria. "Anti-inflammatory effects in acute kidney injury (AKI) are mediated via the netrin-1 receptor UNC5B by the downregulation of inflammatory cytokines." (PMID 35008701, 2021).
acute myocardial infarction (1 paper, 2021). Necrosis of the myocardium, as a result of interruption of the blood supply to the area. "Specifically, a progressive increase in Netrin-1 and UNC5b was evidenced going from controls to stable angina (SA) and acute myocardial infarction (AMI) patients." (PMID 33567662, 2021).
Arthritis (1 paper, 2019). Inflammation of a joint. "All cells used in the inflammation such as neutrophils, monocytes, macrophages, synovial fibroblasts, and bone destruction characterize this model of arthritis express the UNC-5B and netrin-1 in addition to its effects on leukocyte migration." (PMID 31663032, 2019).
colon adenocarcinoma (1 paper, 2021). "Accordingly, a positive correlation (r = 0.406; P < 0.0001) between UNC5B-Δ8 and NOVA2 expression levels was present in the TCGA-Colon Adenocarcinoma (TCGA-COAD) dataset." (PMID 34381052, 2021).
colorectal adenocarcinoma (1 paper, 2023). The most common type of colorectal carcinoma. "Furthermore, both NTN-1 and ACM were found to increase NEO1 and DCC mRNA levels in two colorectal adenocarcinoma cell lines, together with UNC5B downregulation in HT-29 cells when stimulated with ACM." (PMID 36831381, 2023).
depression (1 paper, 2023). "The potential target genes Ntn1, Unc5b, Ptpn11, and Src are included in this pathway and participate in the process of psychiatric disorders such as depression." (PMID 37091805, 2023).
endothelial dysfunction (1 paper, 2021). In vascular diseases, endothelial dysfunction is a systemic pathological state of the endothelium (the inner lining of blood vessels) and can be broadly defined as an imbalance between vasodilating and vasoconstricting substances produced by (or acting on) the endothelium. "By providing morphological and functional evidence, we showed that UNC5B induced endothelial cell senescence by inhibiting cell proliferation causing endothelial dysfunction by impairing tube formation and migration." (PMID 34239689, 2021). "Our preliminary research indicated that UNC5B participated in restoring endothelial cell senescence and age-related endothelial dysfunction with young human plasm." (PMID 34239689, 2021).
gastric cancer (1 paper, 2022). A primary or metastatic malignant neoplasm involving the stomach. "UNC5B is known to inhibit cell proliferation by inducing cell cycle arrest, and ANXA6 has been reported to induce cell cycle arrest in gastric cancer." (PMID 35457039, 2022).
gliosarcoma (1 paper, 2019). A rare histological variant of glioblastoma (WHO grade IV) characterized by a biphasic tissue pattern with alternating areas displaying glial and mesenchymal differentiation (WHO). "More interestingly, we found several genes highly up-regulated in gliosarcoma, including the genes encoding proteins putatively related to differentiation: UNC5B, a metallopeptidase (ADAMTS4) and a collagen COL18A1, in comparison to GBMs (log2 fold change)." (PMID 30818875, 2019).
hepatocellular carcinoma (1 paper, 2022). A malignant tumor that arises from hepatocytes. "UNC5B expression is associated with vascular formation in hepatocellular carcinoma." (PMID 35035481, 2022). "Downregulation of UNC5B may promote angiogenesis in hepatocellular carcinoma." (PMID 35035481, 2022).
inflammatory bowel disease (1 paper, 2014). A spectrum of small and large bowel inflammatory diseases of unknown etiology. "In conclusion, a therapy based on the activation of UNC5B-mediated cell survival pathway may help to treat inflammatory bowel disease." (PMID 24720832, 2014).
myocardial ischemia (1 paper, 2013). A disorder of cardiac function caused by insufficient blood flow to the muscle tissue of the heart. "Given that this process is a critical step during the pathophysiology of myocardial ischemia followed by reperfusion (IR) we investigated the role of UNC5B during myocardial IR." (PMID 23936025, 2013). "Following myocardial ischemia reperfusion injury infarct sizes were significantly diminished in UNC5B+/− (23±4% of AAR) mice compared to WT animals (47±1%)." (PMID 23936025, 2013). "In-vivo, using a model of acute myocardial ischemia in UNC5B+/− and wild type (WT) animals, we found a significant reduction of infarct sizes in UNC5B+/− animals." (PMID 23936025, 2013). "We found that functional inhibition of UNC5B in mice before the onset of myocardial ischemia was protective against myocardial tissue injury." (PMID 23936025, 2013). "Furthermore, the repression of UNC5B through siRNA, the inhibition through anti-UNC5B antibody and the depletion of neutrophils demonstrated a significant importance of UNC5B for the extent of myocardial ischemia reperfusion injury." (PMID 23936025, 2013).
Parkinson disease (1 paper, 2023). A progressive degenerative disorder of the central nervous system characterized by loss of dopamine producing neurons in the substantia nigra and the presence of Lewy bodies in the substantia nigra and locus coeruleus. "Consistent with this notion, UNC5B has been linked to neurodegeneration in the 6-OHDA model of Parkinson’s disease and UNC5C has been nominated as a risk allele in late-onset AD." (PMID 37039476, 2023).
peripheral nerve injury (1 paper, 2021). Injury to a peripheral nerve. "Our findings suggest that Netrin-4 induced by peripheral nerve injury causes neuropathic pain via Unc5B." (PMID 33914819, 2021).
peritonitis (1 paper, 2025). Inflammation of the peritoneum (tissue that lines the abdominal wall and covers most of the organs in the abdomen). "For example, Unc5b is known to be constitutively expressed in monocytes, granulocytes, and lymphocytes, and Neo1 expression has been reported in Ly6Chi inflammatory monocytes in sterile peritonitis models." (PMID 40728980, 2025).
pituitary adenoma (1 paper, 2021). "The results from WES and targeted resequencing and clinical results from GH-secreting pituitary adenoma patients confirmed that variants in BCHE, DARS, NGDN, and UNC5B may be involved in GH secretion." (PMID 34400688, 2021). "However, some variants were associated with the biochemical activities of GH-secreting pituitary adenoma, such as BCHE, DARS, NGDN, and UNC5B variants." (PMID 34400688, 2021).
pituitary tumor (1 paper, 2021). A benign or malignant neoplasm affecting the pituitary gland. "BCHE, DARS, NGDN, and UNC5B variants were associated with increased GH-secreting pituitary tumor biochemical activity, which was confirmed in vitro." (PMID 34400688, 2021). "Furthermore, GH-secreting pituitary tumors with variants in BCHE, DARS, NGDN, and UNC5B presented high biochemical activities including GH and IGF-1." (PMID 34400688, 2021).
rectal cancer (1 paper, 2021). A primary or metastatic malignant neoplasm that affects the rectum. "On the contrary, in the presence of Netrin‐1, UNC5B is regulated to promote the proliferation and migration in rectal cancer." (PMID 33345442, 2021).
retinoblastoma (1 paper, 2024). A malignant tumor that originates in the nuclear layer of the retina. "YAP, YAP5SA, and TEAD4(DBD)-VP64, but not controls, also induced UNC5B in WERI-RB1 retinoblastoma cells." (PMID 39172021, 2024). "Thus, UNC5B protein-induction was detected in multiple lines, UNC5B-knockout countered YAP-induced cytostasis in Y79 retinoblastoma cells, and a Netrin blocking antibody and a Netrin trapping reagent (UNC5-Fc) also had this anticytostatic effect across multiple YAPoff cancer cell lines." (PMID 39172021, 2024). "Interestingly, UNC5B was already highly expressed in many SCLC (NCI-H69, NCI-N417, NCI-H82) and some other YAPoff cell lines (retinoblastoma/RB1021, neuroendocrine prostate/NCI-H660) relative to YAPon lines, which may explain why YAP does not further increase expression in some contexts." (PMID 39172021, 2024). "Examination of RNA-Seq data from retinoblastoma and SCLC revealed up-regulation of multiple UNC5 and NTN members following forced YAP expression, including UNC5B/C/D and NTN1, but not NTN3." (PMID 39172021, 2024).
rotator cuff tear (1 paper, 2025). "In this study, we demonstrate for the first time that netrin-1 and its dependence receptors UNC5B and Neogenin-1 are coordinately upregulated in a rat rotator cuff tear model, with peak expression in the subacute phase of tendon injury." (PMID 40728980, 2025).
schwannoma (1 paper, 2017). A benign, usually encapsulated slow growing tumor composed of Schwann cells. "Knockdown Unc5B in RT4 schwannoma cell using Unc5B specific RNAi significantly reduced Netrin-1 induced RT4 schwannoma cell proliferation." (PMID 28245592, 2017). "An examination of Netrin-1 receptor mRNA expression using RT-PCR in RT4 schwannoma cells and primary rat Schwann cells found that RT4 schwannoma cells and rat Schwann cells strongly expressed Unc5B." (PMID 28245592, 2017).
scleroderma (1 paper, 2023). Scleroderma is a rare autoimmune connective tissue disorder characterized by abnormal hardening of the skin and, sometimes, other organs. "It was further found to promote angiogenesis by blocking apoptosis induced by UNC5B—the apoptosis of ECs being a key mechanism in scleroderma." (PMID 37443817, 2023).
Sepsis (1 paper, 2021). Sepsis is defined as life-threatening organ dysfunction caused by a dysregulated host response to infection. "The transfection of pcDNA-netrin-1 increased netrin-1 and UNC5B expression, which resulted in a prevention of lung injury caused by sepsis." (PMID 35008701, 2021). "In a sepsis rat model, levels of netrin-1 and its receptor UNC5B were downregulated." (PMID 35008701, 2021).
thyroid (1 paper, 2020). "In this study, targeted inhibition of TNRC6C-AS1 with shRNA decreased cell proliferation, migration, and invasion in ATC cell lines through downregulation of UNC5B expression and inhibited thyroid tumorigenesis in vivo." (PMID 32760219, 2020).